PLN (phospholamban)
Diseases named in the same sentence as PLN in open-access papers (continued):
Sharing a sentence is not in itself a finding about the gene and the disease.
cardiomyopathy (continued). "Among these mutants, the R14del mutation in PLN is the most prevalent in cardiomyopathy patients in the Netherlands and is found in 15% of idiopathic DCM and 12% of ACM patients." (PMID 35699837, 2022). "PLN mutants, such as PLN R14del, R9C, and L39X, are associated with severe cardiomyopathy that can lead to HF." (PMID 35699837, 2022). "In this review, we will summarize the development regarding precision medicine for genetic cardiomyopathies over the last decade, with a special focus on Phospholamban (PLN)-R14del-associated cardiomyopathy." (PMID 35699837, 2022). "In this review we consider the current scientific evidences for the connection between suppression of lusitropy and cardiac dysfunction in the context of mutations in phospholamban and thin filament proteins that are associated with cardiomyopathies." (PMID 36698941, 2022). "We have previously reported that, like in human patients, intracardiomyocyte aggregation of PLN proteins is an early hallmark of PLN-R14del cardiomyopathy in mice." (PMID 35269571, 2022). "PLN R14del-associated cardiomyopathy is a very detrimental disease with a poor prognosis, and a large group of the patient population ultimately find themselves in need of a left ventricular assist device or cardiac transplantation." (PMID 35699837, 2022). "Due to the relatively high prevalence of PLN R14del-associated cardiomyopathy in the Netherlands, many studies are currently performed to identify disease modifiers and pathophysiology, and what can be done to prevent disease development." (PMID 35699837, 2022). "PLN R14del-associated cardiomyopathy is an excellent example of a genetic disease in urgent need of deep phenotyping to elucidate the causal biological mechanisms of disease and finding a precision medicine for this cardiomyopathy population." (PMID 35699837, 2022). "In a homozygous PLN R14del-associated cardiomyopathy mouse model, we have shown that the PLN-ASO prevents PLN protein aggregation and cardiac dysfunction, as well as leading to a 3-fold increase in survival rate [54•]." (PMID 35699837, 2022). "With regard to PLN R14del-associated cardiomyopathy, the most promising modality of precision medicine is gene editing." (PMID 35699837, 2022). "PLN R14del, a genetic mutation known to cause cardiomyopathy, will be used as an example to describe the potential and pitfalls of precision medicine." (PMID 35699837, 2022). "The clinical phenotype of PLN R14del-associated cardiomyopathy is characterized by cardiac fibrosis, PLN protein aggregation, fibrofatty replacement, and decreased ECG potentials." (PMID 35699837, 2022). "Patients suffering of PLN R14del-associated cardiomyopathy are treated like any other type of patients with HF, though the etiology is very different from standard HF." (PMID 35699837, 2022). "Since then, the PLN mutationR14del has been identified in an increasing number of patients around the world, with this PLN genetic variant being the most prevalent cardiomyopathy-related mutation in the Netherlands (>1000 patients)." (PMID 35805951, 2022). "This study identified impairment of the ER/mitochondria compartment without SR dysfunction as a novel disease mechanism underlying PLN p.Arg14del cardiomyopathy." (PMID 33998164, 2021). "The primarily “dilative” remodeling of PLN p.Arg14del-associated cardiomyopathy, which misses a proper “hypertrophic” phase, would be consistent with such a mechanism." (PMID 34948294, 2021). "In conclusion, accumulation of p62‐positive protein aggregates is homogeneously distributed in the myocardium independently of fibrosis distribution and strongly associated with desmin and phospholamban cardiomyopathy." (PMID 33605084, 2021). "In hearts of cardiomyopathy patients with a pathogenic variant in the gene encoding phospholamban (PLN), we have recently demonstrated aggregates that are both p62 and phospholamban positive." (PMID 33605084, 2021).
cardiomyopathy (continued). "PLN R14del is a Dutch founder mutation and the most prevalent cardiomyopathy-related mutation in the Netherlands." (PMID 34887420, 2021). "In conclusion, accumulation of p62‐positive protein aggregates is homogeneously distributed in the myocardium independently of fibrosis distribution and associated with desmin and phospholamban cardiomyopathy." (PMID 33605084, 2021). "A PLN-p.R14del mouse model was established due to its being a prominent cause of cardiomyopathy within the Netherlands." (PMID 32466575, 2020). "Several PLN mutations have been identified, with the R14del mutation being the most prevalent cardiomyopathy-related mutation in the Netherlands." (PMID 30547415, 2019). "In the Netherlands the PLN R14del mutation is one of the most prevalent cardiomyopathy-related mutations." (PMID 30547415, 2019). "Diet has been shown to play a key role with birds fed a high protein diet twice as likely to suffer death as a result of cardiomyopathy, but variations in Troponin T and phospholamban (PLN) have also been linked to DCM." (PMID 29367539, 2017). "In conclusion, we have identified the previously characterised c.25C > T PLN mutation that segregates with severe DCM in a South African kindred following the screening of 315 patients with different types of cardiomyopathy." (PMID 26917049, 2016). "One of the genes implicated in cardiomyopathy is phospholamban (PLN), which encodes the phospholamban protein that is involved in calcium signalling and muscle contraction." (PMID 26917049, 2016). "While the majority of these PLN mutations have been associated with severe cardiomyopathy, only PLN mutations associated with DCM meet the strict criteria to be called definitively pathogenic." (PMID 26917049, 2016). "PLN mutations are a rare cause of cardiomyopathy in South Africans which should be added to screening panel for cardiomyopathy in the country." (PMID 26917049, 2016). "The aim of this study was to determine if PLN is a cause of cardiomyopathy in Africans, and explore the possibility of PLN founder mutations common between the African population and individuals with European ancestry." (PMID 26917049, 2016). "In this study, we derived iPSC-CMs from a patient with cardiomyopathy associated with a PLN R14del mutation to better understand the link between mutant R14del and cardiac pathophysiology." (PMID 25923014, 2015). "As this has not been studied before, the aim of our project was to determine the prevalence of PLN mutations in Polish cardiomyopathy patients." (PMID 25928149, 2015). "In conclusion, in PLN p.Arg14del mutation associated cardiomyopathy myocardial fibrosis is predominantly present in the left posterolateral wall, whereas fatty changes are more pronounced in the wall of the right ventricle." (PMID 24732829, 2014). "The aim of this study was to determine the exact patterns of fibrosis and fatty changes in the myocardium of patients with the PLN p.Arg14del mutation associated cardiomyopathy in relation to their clinical phenotype." (PMID 24732829, 2014). "In PLN p.Arg14del mutation associated cardiomyopathy, myocardial fibrosis is predominantly present in the left posterolateral wall and to a lesser extent in the right ventricular wall, whereas fatty changes are more pronounced in the right ventricular wall." (PMID 24732829, 2014). "Since the focus of this study was the PLN RΔ14 mutation that causes human cardiomyopathy, we carried out further staining for this construct in larger, more defined primary fibroblasts." (PMID 20634894, 2010). "The R14Δ-PLN mutation causes severe cardiomyopathy that is resistant to conventional treatment." (PMID 39446877, 2024). "Instead of altered calcium SR uptake, the formation of perinuclear PLN protein clusters that cause disorganization of the SR and subsequent cardiomyocyte death has recently emerged as the main mechanism for HF development in this cardiomyopathy." (PMID 38334971, 2024).
cardiomyopathy (continued). "Pathogenic variants in the PLN gene may cause inherited cardiomyopathies due to a key role in the function of the sarcoplasmic reticulum (SR) which is the main dynamic Ca2+ storage compartment of the cell." (PMID 38392255, 2024). "Patients with an LVEF percentage between 40 and 50% and with specific forms of cardiomyopathy, such as those due to genetic mutations (e.g., Lamin A/C, filamin-C, and phospholamban), arrhythmogenic LV CMP, or hypertrophic CMP, may require ICD therapy." (PMID 38786970, 2024). "The immunohistochemical identification of PLN positive aggregates proved to be selective for the Arg14del mutation, thus validating the use of PLN immunostaining in cardiac muscle biopsy for the diagnosis of Arg14del-mutated cardiomyopathy." (PMID 37408239, 2023). "Since PLN-R14del proteins resulting from the p.(Arg14del) pathogenic variant are the root cause of PLN-R14del cardiomyopathy, elimination of the mutant protein could be a promising therapeutic approach." (PMID 35269571, 2022). "Several PLN mutations are known to cause cardiomyopathy in humans, with the deletion of arginine at position 14 of the PLN protein (R14del) being one of the most prevalent variants which leads to severe HF and malignant ventricular arrhythmias, and has recently been increasingly studied." (PMID 34462437, 2021). "An R4344Q knock-in mouse developed a cardiomyopathy-like phenotype with abnormal Ca2+-handling and arrhythmias, which were attributed to an enhanced affinity of a putative interaction between obscurin Ig58 and phospholamban (PLN) due to the R4344Q variant." (PMID 33438037, 2021). "Here the authors show that zebrafish with the PLN p.Arg14del mutation develop severe cardiomyopathy which is preceded by contractile dysfunction and altered calcium dynamics and istaroxime is identified as a small molecule that can rescues some of these phenotypes." (PMID 34887420, 2021). "The observed variability of the phenotype raises the possibility that a yet to be identified pathogenic modifier variant could be present with the PLN-R14Del mutation and contribute to the development of the cardiomyopathy." (PMID 32878278, 2020). "In addition to the findings in PLN-R14Δ/+ mice, we observed that PLN-R14Δ/Δ mice exhibited the same cardiac phenotype as human cardiomyopathy patients that carry this pathogenic variant, but in an accelerated manner." (PMID 32555305, 2020). "Aggregation of PLN proteins in the cardiomyocytes and insufficiency of the PCQ system to correct this, could play a causal role in the pathophysiology of PLN-R14del-related cardiomyopathy." (PMID 32555305, 2020). "Investigating the effect of different disease modifiers in PLN-R14Δ/+ mice could identify risk factors for this type of cardiomyopathy." (PMID 32555305, 2020). "Variants in PLN often result in phospholamban cardiomyopathy, a distinct form of cardiomyopathy with SERCA2 dysfunction that has an overlap of clinical features of ACM and may be considered a form of ACM itself." (PMID 32466575, 2020). "In conclusion, we have generated a novel mouse model carrying the PLN-R14del pathogenic variant, and PLN-R14Δ/Δ mice mimic human disease in a strikingly comparable but accelerated manner, whereas PLN-R14Δ/+ mice exhibit cardiomyopathy at middle age similar to human carriers." (PMID 32555305, 2020). "Pathogenic mutations in the phospholamban (PLN) gene may cause inherited cardiomyopathies due to the role of PLN in calcium homeostasis." (PMID 30547415, 2019). "Pathogenic mutations in the phospholamban (PLN) gene may give rise to inherited cardiomyopathies due to its role in calcium homeostasis." (PMID 30547415, 2019). "As this mutation arose 575–825 years ago, the possibility exists that the PLN p.R14del founder mutation may be present in descendants of Dutch settlers and may cause cardiomyopathy in a subset of individuals of European descent in Southern Africa13." (PMID 26917049, 2016).
cardiomyopathy (continued). "In Poland, similar to most populations, PLN mutations rarely cause cardiomyopathy." (PMID 25928149, 2015). "Although Pln mutations either resulting in elevated PLN expression or reduced PLN phosphorylation have been causally linked to human cardiomyopathy, it is unknown whether these mutations can affect skeletal muscle health." (PMID 26035394, 2015). "Our purpose was to identify PLN mutations in Polish cardiomyopathy patients." (PMID 25928149, 2015). "The sensitivity of endomyocardial biopsies from the right ventricular septum in AC is low, according to our findings this might also be the case in PLN mutation associated cardiomyopathies." (PMID 24732829, 2014). "The lack of a known ER retention sequence in PLN and the finding that the deletion of arginine 14 causes lethal human cardiomyopathy led us to create a PLN RΔ14 construct as well as a series of constructs that contain mutations in one or both arginine residues." (PMID 20634894, 2010). "However, in humans, PLN silencing has been associated with lethal cardiomyopathy." (PMID 35324727, 2022). "Though pathogenic variants in PLN are rare, findings from PLN mutant carriers and mouse models demonstrate that changes in calcium handling in the presence of Phospholamban pathogenic variants, secondary to perturbations in SERCA2a activity, are sufficient to cause cardiomyopathy." (PMID 29119312, 2017). "In Africa, the prevalence of PLN mutations in cardiomyopathy patients is unknown." (PMID 26917049, 2016). "While PLN-ASO enhances calcium cycling, its primary therapeutic effect in PLN-R14del cardiomyopathy is by reducing harmful PLN-SR clusters." (PMID 40905134, 2025). "Altogether, the current study shows that PLN-ASO therapy has limited effects on calcium handling in PLN-R14del cardiomyopathy." (PMID 40905134, 2025). "This implies that PLN-ASO therapy acts predominantly via restoration of SR structure in PLN-R14del cardiomyopathy." (PMID 40905134, 2025). "Together, these data indicate that the therapeutic effect of PLN silencing in PLN-R14del cardiomyopathy is primarily mediated by improvements in SR structure rather than by enhanced calcium cycling." (PMID 40905134, 2025). "In conclusion, this study demonstrates a dose-dependent protective effect of ASO treatment in PLN-R14del cardiomyopathy mice." (PMID 40905134, 2025). "Taken together, this study provides evidence for altered ER calcium loading as a new disease mechanism in PLN-R14del cardiomyopathy." (PMID 40791987, 2025). "Homozygous PLN-R14del knock-in mice showed a strong cardiomyopathy phenotype, accompanied by histological evidence of PLN aggregate formation." (PMID 40791987, 2025). "For PLN-R14del cardiomyopathy, the striking resemblance of human disease recapitulated by the mouse model has been extensively described before." (PMID 38334971, 2024). "Among the 50 unique cardiomyopathy genes with truncating mutations, MYBPC3, TNNT2, and phospholamban (PLN) exhibited a high ratio of cases compared to reference populations for HCM." (PMID 38406555, 2024). "We showed that overexpression of dwarf open reading frame (DWORF), a protein counteracting the function of PLN in the SR, delayed PLN-R14del cardiomyopathy and extended life span in a mouse model for this disease." (PMID 38334971, 2024). "modeled the PLN R14del cardiomyopathy with isogenic pairs of hiPSC‐CMs, and single‐cell RNA sequencing revealed that the unfolded protein response pathway (UPR) had been induced in PLN R14del." (PMID 39465141, 2024). "Our results demonstrate that PLN mutant p.Leu39*-related cardiomyopathy is mainly characterized by a hypertrophic phenotype with a potential to evolve towards a dilated phenotype." (PMID 38392255, 2024). "Let us use the phospholamban (PLN) p.(Arg14del) cardiomyopathy as an example, in which penetrance of the disease is highly variable, with an arrhythmogenic phenotype presenting at a younger age than the dilated cardiomyopathy phenotype." (PMID 37491506, 2023).
cardiomyopathy (continued). "One of these genes, the gene encoding phospholamban (PLN), has shown definitive evidence of association with cardiomyopathy." (PMID 36622581, 2023). "Carriers of PLN p.(Arg14del) can be diagnosed with either of these cardiomyopathies, reflecting the clinical and genetic overlap between these disease entities." (PMID 37958923, 2023). "We know PLN p.(Arg14del) cardiomyopathy is an autonomically progressive disorder with protein aggregates, left ventricular (LV) fibrosis and dysfunction, features that cannot be reversed." (PMID 37493902, 2023). "Despite the well-defined genetic etiology, the molecular mechanism driving the pathogenesis of PLN R14del-cardiomyopathy remains elusive." (PMID 38107262, 2023). "Although I am an optimist by nature, phospholamban (PLN) p.(Arg14del) cardiomyopathy is a highly malignant condition that must be avoided at all costs." (PMID 37493902, 2023). "We have recently characterized the PLN-R14del mouse model, and have described that PLN-R14 Δ/Δ mice rapidly and progressively develop cardiomyopathy with severe HF between 3 and 8 weeks of age." (PMID 35269571, 2022). "This is particularly true in PLN p.Arg14del cardiomyopathy, where we find significant clinical overlap." (PMID 34143416, 2022). "In conclusion, the results of this study implicate that PLN-ASO exerts beneficial effects in PLN-R14del cardiomyopathy when administered after disease onset." (PMID 35269571, 2022). "In case of a primary genetic defect, such as PLN-R14del, understanding and targeting the molecular mechanisms that lead to cardiomyopathy is key for successful therapy." (PMID 35269571, 2022). "Analogous to other inherited cardiomyopathies, the natural course of PLN p.Arg14del cardiomyopathy is age-related; after a presymptomatic phase of variable length, many PLN p.Arg14del carriers progress to overt cardiomyopathy." (PMID 34143416, 2022). "Our data present possible early disease mechanisms in PLN R14del cardiomyopathy and provide usefulness of this model to explore patient-specific drug treatment." (PMID 34887420, 2021). "Compared to gene therapy utilized in earlier studies, these promising results in rodent models of MI, in PLN R14del related cardiomyopathy and DCM (Cspr3/Mlp−/−), highlight the therapeutic potential of targeting cardiac PLN35,44,45." (PMID 34462437, 2021). "Another typical hallmark of PLN R14del cardiomyopathy in humans is a low voltage ECG, which was also observed in PLN R14Δ/Δ mice (expressed by low R-amplitude), and was partially restored by PLN-ASO treatment (0.84 ± 0.05 vs. 0.55 ± 0.05 mV, P value < 0.0001)." (PMID 34462437, 2021). "This prevents or reverses cardiac dysfunction in three different rodent models of HF and cardiomyopathy, and significantly increases lifespan in a model of hereditary PLN R14del cardiomyopathy." (PMID 34462437, 2021). "Mutations in PLN are known to cause a-DCM and ACM and among the identified mutations, the PLN-R14Del mutation is the most prevalent cardiomyopathy-associated mutation in the Netherlands (founder effects)." (PMID 32878278, 2020). "Administration of standard HF therapy does not rescue the phenotype, underscoring the need for better understanding of the pathophysiology of PLN-R14del-related cardiomyopathy, and PLN-targeted therapy." (PMID 32555305, 2020). "The most common subtype of ACM is arrhythmogenic right ventricular cardiomyopathy (ARVC); however, left and biventricular dominant forms of the disease are well documented, including lamin types A/C (LMNA) and phospholamban (PLN) cardiomyopathies." (PMID 32466575, 2020). "The ARVC and DCM forms of PLN-R14del induced cardiomyopathy seem to have different mechanism despite the same genetic causes and need to be treated distinctively." (PMID 33020536, 2020). "Possibly, the expression level or accumulation of the PLN-R14del protein has to exceed a certain threshold to trigger cardiomyopathy." (PMID 32555305, 2020).